PAK4 (p21 (RAC1) activated kinase 4)
Description:
Serine/threonine-protein kinase that plays a role in a variety of different signaling pathways including cytoskeleton regulation, cell adhesion turnover, cell migration, growth, proliferation or cell survival. Activation by various effectors including growth factor receptors or active CDC42 and RAC1 results in a conformational change and a subsequent autophosphorylation on several serine and/or threonine residues. Phosphorylates and inactivates the protein phosphatase SSH1, leading to increased inhibitory phosphorylation of the actin binding/depolymerizing factor cofilin. Decreased cofilin activity may lead to stabilization of actin filaments. Phosphorylates LIMK1, a kinase that also inhibits the activity of cofilin. Phosphorylates integrin beta5/ITGB5 and thus regulates cell motility. Phosphorylates ARHGEF2 and activates the downstream target RHOA that plays a role in the regulation of assembly of focal adhesions and actin stress fibers. Stimulates cell survival by phosphorylating the BCL2 antagonist of cell death BAD. Alternatively, inhibits apoptosis by preventing caspase-8 binding to death domain receptors in a kinase independent manner. Plays a role in cell-cycle progression by controlling levels of the cell-cycle regulatory protein CDKN1A and by phosphorylating RAN. Promotes kinase-independent stabilization of RHOU, thereby contributing to focal adhesion disassembly during cell migration.
Tractability: Small molecule: a drug acting on it is in phase 1 trials; a structure with a bound ligand is known; a high-quality ligand is known; it has a high-quality binding pocket; it belongs to a druggable protein family. Antibody: the Human Protein Atlas places it where antibodies can reach. PROTAC: it is named in the literature on targeted protein degradation; UniProt records ubiquitination sites on it; ubiquitination databases record sites on it; its protein half-life has been measured; a small molecule that binds it is known.
Target class: Protein Kinase; STE protein kinase PAKB subfamily; STE protein kinase STE20 family; STE protein kinase group; Enzyme; Kinase
Chemical probes: GNE-2861, PD134681, PF-03758309
Gene: Protein-coding gene on chromosome 19 (39,125,728 to 39,182,816, forward strand). Ensembl gene ENSG00000130669.
Subcellular location: Cytoplasm
Subcellular location (Human Protein Atlas): Cell Junctions; Plasma membrane
Pathways (Reactome):
Signal Transduction: CDC42 GTPase cycle; RAC1 GTPase cycle; RAC2 GTPase cycle; RAC3 GTPase cycle; RHOG GTPase cycle; RHOH GTPase cycle; RHOJ GTPase cycle; RHOQ GTPase cycle; RHOU GTPase cycle; RHOV GTPase cycle
Developmental Biology: Activation of RAC1
Gene Ontology:
Molecular function: cadherin binding involved in cell-cell adhesion; protein binding; protein serine/threonine kinase activity; protein-macromolecule adaptor activity; protein kinase activity; ATP binding; protein serine kinase activity
Biological process: negative regulation of endothelial cell apoptotic process; positive regulation of angiogenesis; positive regulation of focal adhesion disassembly; protein stabilization; apoptotic process; cell migration; cellular response to starvation; cytoskeleton organization; regulation of cell growth; regulation of MAPK cascade; signal transduction; cell-cell adhesion; negative regulation of triglyceride catabolic process
Cellular component: adherens junction; cell junction; cytoplasm; focal adhesion; plasma membrane; cytosol; Golgi apparatus
Genetic constraint (gnomAD): Loss-of-function variants: 49 observed, 49.04 expected, observed/expected ratio (o/e) 1, 90% interval 0.79 to 1.27. The upper end of that interval is the gene's LOEUF score, 1.27, which puts it in group 5 of 6, group 1 being the genes least tolerant of losing a copy. Missense variants: 824 observed, 799.16 expected, observed/expected ratio (o/e) 1.03, 90% interval 0.97 to 1.09. Synonymous variants: 376 observed, 341.91 expected, observed/expected ratio (o/e) 1.1, 90% interval 1.01 to 1.2.
Homologues: Orthologues: chimpanzee PAK4 (99% identical), macaque PAK4 (98% identical), dog PAK4 (95% identical), pig PAK4 (95% identical), guinea pig PAK4 (94% identical), mouse Pak4 (93% identical), rat Pak4 (93% identical), rabbit PAK4 (86% identical), tropical clawed frog pak4 (74% identical), zebrafish pak4 (70% identical). Paralogues in human: PAK5 (62% identical), PAK6 (52% identical), PAK1 (34% identical), PAK2 (34% identical), PAK3 (34% identical), MAP3K19 (22% identical), MAP3K1 (21% identical), NRK (19% identical), STK39 (19% identical), MAP4K3 (19% identical), TNIK (19% identical), MAP4K4 (19% identical), and 23 more.
Diseases named in the same sentence as PAK4 in open-access papers:
PAK4 is named in the same sentence as 114 diseases in open-access papers, as found by Europe PMC text mining. Sharing a sentence is not in itself a finding about the gene and the disease. The quoted sentences say what the papers report.
breast cancer (54 papers, 2012 to 2026). A primary or metastatic malignant neoplasm involving the breast. "PAK4 overexpression was associated with shorter survival and poor prognosis in some cancers, such as non-small cell lung cancer, ovarian cancer, and breast cancer." (PMID 39337621, 2024). "A higher expression of PAK4 was associated with the shorter survival of breast cancer patients who are treated with endocrine therapy or tamoxifen." (PMID 36980457, 2023). "We next analyzed the role of nPAK4 in conferring invasive phenotypes to breast cancer cells using approaches involving the loss or gain of PAK4 functions by using knockdown (shPAK4) and overexpression (PAK4-Lv) approaches." (PMID 30177834, 2019). "In support of a potential clinical relevance, we also found that low PAK4/high RELB expression was associated with better prognosis in the HER2-positive breast cancer subtype, in which PAK4 expression was the highest." (PMID 31399573, 2019). "PAK4 wt overexpression caused hyperplasia and, at a later stage, mammary tumors in a fraction of the mice comparable to the overexpression of catalytically active PAK140." (PMID 31399573, 2019). "We report that PAK4 is overexpressed in all human breast cancer subtypes and associated with poor patient outcome." (PMID 31399573, 2019). "Since PAK5 and PAK6 proteins are less frequently associated with breast cancer, our focus for this study was PAK4, but further investigation is warranted." (PMID 28198380, 2017). "Though previous studies have demonstrated that PAK4 expression is associated with aggressive oncogenic activity in breast cancer cells, those studies had performed either in the breast cancer cell lines or mouse mammary gland tumor." (PMID 28407679, 2017). "Herein, we analyzed the PAK4 expression level in tumor tissue from 93 breast cancer patients, and also evaluated the association of PAK4 with clinical pathological parameters and patient survival." (PMID 28407679, 2017). "It has been shown that PAK4-overexpression is associated with the tumorigenic potential of human breast cancer cells in athymic mice." (PMID 25238288, 2014). "We have found that Pak4 has an important role in mammary cell transformation, but other Pak family members have also been implicated in breast cancer." (PMID 23732710, 2013). "Pak4 is a serine/threonine kinase and found to be highly expressed in breast cancer and associated with a signaling pathway leading to malignancy and formation of mammary tumors in nude mice." (PMID 23401782, 2013). "Interestingly, PAK4 is closely associated with the activity of cancer stem-like cells (CSCs) in metastatic ER+ breast cancer." (PMID 41596432, 2026). "Furthermore, the loss of cell adhesion caused by PAK4 methylation is correlated with defective migration and proliferation of breast cancer cells." (PMID 40102573, 2025). "PAK4 has been implicated in some types of cancer due to its role in regulating cell growth and it is overexpressed in many types of cancer cells, including breast cancer, kidney cancer, pancreatic cancer, ovarian cancer, and colorectal cancer." (PMID 39337621, 2024). "The results demonstrate a novel mechanism underlying PAK4 promoting ERα-positive breast cancer-induced osteolysis in the bone microenvironment, suggesting that PAK4 may be a therapeutic target for ERα-positive breast cancer osteolytic bone destruction." (PMID 32549768, 2020). "Although this study has suggested that nuclear PAK4 modulates breast cancer bone metastasis, the underlying molecular mechanism for osteolytic bone destruction remains unclear." (PMID 32549768, 2020). "Here we show that PAK4 is overexpressed in breast cancer associated with poor prognosis." (PMID 31399573, 2019). "Importantly, while overexpression of PAK4 caused decreased sensitivity to tamoxifen in MCF7 human breast cancer cells, a specific inhibitor of group II PAKs, GNE-2861, restored the sensitivity to tamoxifen in the tamoxifen-resistant MCF-7/LCC2 cells." (PMID 26554417, 2015).
breast cancer (continued). "In addition to serving as a marker for cancer, however, Pak4 can also cause mammary tumors to form, and thus it has a strong potential as a drug target." (PMID 23326684, 2012). "While our study focuses on PAK4 methylation in breast cancer cells, it is known that PAK4 expression is associated with promoting cell migration and invasion in other cancers as well and it remains an open question if PAK4 activity in these cancers is also regulated by SETD6." (PMID 33051544, 2020). "Studies have shown that E2 stimulation significantly increases the expression and activation of PAK4 in ER+ MCF-7 breast cancer cells." (PMID 41596432, 2026). "In summary, the E2/PAK4/Cyclin D1 signaling axis plays a pivotal role in regulating proliferation, cancer stemness, and bone-specific metastatic behavior in ER+ breast cancer." (PMID 41596432, 2026). "Upon E2 stimulation, PAK4 interacts with ERα and translocates from the cytoplasm into the nucleus (nPAK4) in ER+ breast cancer cells." (PMID 41596432, 2026). "This suggests that PAK4 mediates the phenotypic and functional changes in breast cancer cells induced by RBCs." (PMID 40301999, 2025). "The nuclear PAK4-Erα-LIFR axis facilitates bone metastasis of ER+ breast cancers by initiating an EMT program, where high expression of nPAK4 is often associated with a poorer prognosis." (PMID 40977686, 2025). "In breast cancer cells, PAK4 methylation by SETD6 significantly attenuated cell adhesion by causing the mislocalization of paxillin, a PAK4 substrate, thereby promoting the disassembly of focal adhesions." (PMID 40102573, 2025). "In ER+ breast cancers, nuclear p21-activated kinase 4 (nPAK4) targets LIFR, augmenting the PAK4-ER axis-mediated bone metastases, and functions as a novel repressor of ERα-mediated transactivation, operating in an E2-dependent manner." (PMID 40977686, 2025). "KPT-9274, a PAK4 inhibitor, significantly reduces the growth of triple-negative breast cancer cells and mammary tumors in mouse models, and it also inhibits the growth of several other types of cancer cells." (PMID 39337621, 2024). "ZIC2 can transcriptional regulates Src, lncRNA SNHG12, Axin2, Runx2, OCT4, STAT3, PAK4 expression in non-small cell lung cancer, endometrial cancer, colon cancer, ccRCC, lung adenocarcinoma, liver cancer, and breast cancer 15, 28, 36-41." (PMID 37496990, 2023). "Targeting the PAK4/MEK/ERK pathway can repress breast cancer progression by inducing G1 phase arrest." (PMID 38132441, 2023). "In breast cancer, PAK4 was expressed in both the nuclei and cytoplasm of cancer cells, and a higher expression of PAK4 predicted the shorter survival of patients." (PMID 36980457, 2023). "PAK4 was involved in resistance to tamoxifen of breast cancer cells and resistance to gemcitabine of pancreatic cancer cells." (PMID 36980457, 2023). "In breast cancer cells, PAK4 was involved in the progression of cancer by preventing senescence-like growth arrest." (PMID 36980457, 2023). "Claudin-4 has been reported to regulate EMT through p21-activated kinase 4 (PAK4) expression in human breast cancer cells." (PMID 37465316, 2023). "The phosphorylation of β-Catenin by PAK1 is required for the ErbB2-induced efficient transformation of mammary epithelial cells, while, PAK4 regulates the stability of p57(Kip2), thereby resulting in the proliferation of breast cancer cells." (PMID 36230657, 2022). "PAK4 localizes to the cytoplasm and nucleus in breast cancer cells, and its expression correlates with an advanced tumor stage." (PMID 35883575, 2022). "MiR-199a-3p inhibits breast cancer cell migration and invasion through downregulation of the PAK4/MEK/ERK signaling pathway." (PMID 35844793, 2022). "The expression of Claudin-4 (CLDN4) is positively correlated with PAK4 in breast cancer and PAK4 induces CCAAT/enhancer binding protein β (CEBPB) activation, resulting in upregulation of CLDN4." (PMID 36105226, 2022).
breast cancer (continued). "Both PAK1 and PAK4 regulate the stemness of breast cancer stem cells, which leads to drug resistance." (PMID 36230657, 2022). "PAK4-driven mammosphere-forming CSC activity increases alongside the progression of breast cancer only in the ER-positive metastatic samples." (PMID 36230657, 2022). "This work will provide fresh insight that the combination of ORFV and PAK4 inhibitors is expected to be a new approach for breast cancer anti-tumor therapy." (PMID 35401439, 2022). "Amplification of the PAK4 gene and dysregulated activation of the PAK4 protein are commonly observed in ovarian cancer, breast carcinoma, and pancreatic carcinoma." (PMID 36105226, 2022). "Studies indicate that PAK4 is commonly highly expressed in a variety of cancers, including breast cancer." (PMID 32549768, 2020). "Studies have shown that PAK4 modulates breast cancer tumorigenesis by activating PI3K/AKT signaling." (PMID 32549768, 2020). "Our previous studies have shown that nuclear PAK4 promotes ERα positive breast cancer bone metastasis." (PMID 32549768, 2020). "Here, we found that PAK4 promotes ERα-positive breast cancer-induced osteolytic bone destruction by phosphorylating RUNX1." (PMID 32549768, 2020). "Here, we demonstrate that PAK4 modulate the regulation of RUNX1 and that the nuclear PAK4 involving in ERα-positive breast cancer-induced osteolytic bone destruction." (PMID 32549768, 2020). "Here we discovered that PAK4 cellular activity is controlled by lysine methylation in breast cancer cells." (PMID 33051544, 2020). "In summary, these findings demonstrate the molecular mechanism of PAK4 promoted osteolytic bone destruction in ERα positive breast cancer." (PMID 32549768, 2020). "It was shown that PAK4 positively controls focal adhesions and downregulation of PAK4 leads to elevated adhesion to fibronectin and a decreased ability to migrate in breast cancer MDA-MB-231 cells." (PMID 33051544, 2020). "Our results suggest PAK4 can be a therapeutic target for ERα-positive breast cancer osteolytic bone destruction." (PMID 32549768, 2020). "Accordingly, palpable mammary tumors appeared considerably later in PAK4 knock-out mice that also presented an extended overall survival." (PMID 32158912, 2020). "To further investigate a potential relationship between PAK4 and NF-κB subunits in breast cancer, we performed correlation analyses for the expression of PAK4 and all NF-κB subunits in the METABRIC dataset." (PMID 31399573, 2019). "PAK4 was firstly abrogated in an extended panel of breast cancer cell lines BT-549, MDA-MB-231, MCF7, and T-47D." (PMID 31399573, 2019). "In summary, our findings establish PAK4 as a promoter of breast cancer development, possibly through overcoming the barrier of OIS." (PMID 31399573, 2019). "We identify PAK4 as an inhibitor of NF-κB signaling in breast cancer and show that the senescence-like growth arrest upon PAK4 knockdown in cancer cells functionally requires the noncanonical NF-κB subunit RELB." (PMID 31399573, 2019). "This inverse correlation was also observed at the protein level in Hs 578T breast cancer cells where PAK4 knockdown upregulated RELB." (PMID 31399573, 2019). "Further raising the potential clinical relevance, we found that PAK4 is overexpressed across all breast cancer subtypes, specifically upregulated during the disease development and correlated with poor prognosis." (PMID 31399573, 2019). "PAK4 is overexpressed in breast cancer cell lines as well as in breast cancer patients, and its overexpression is accompanied by poor patient outcome." (PMID 31594963, 2019). "Different PAK4-depleted breast cancer cell lines exhibited arrest in the G0/G1 or G2/M phases of the cell cycle, as previously reported for cancer cells undergoing senescence." (PMID 31399573, 2019).